MN1 (MN1 proto-oncogene, transcriptional regulator)
Description:
Transcriptional activator which specifically regulates expression of TBX22 in the posterior region of the developing palate. Required during later stages of palate development for growth and medial fusion of the palatal shelves. Promotes maturation and normal function of calvarial osteoblasts, including expression of the osteoclastogenic cytokine TNFSF11/RANKL. Necessary for normal development of the membranous bones of the skull (By similarity). May play a role in tumor suppression (Probable).
Synonyms: MGCR1-PEN; MGCR1; CEBALID; MGCR; dJ353E16.2
Tractability: No criterion of Open Targets' tractability assessment is met for any kind of drug.
Gene: Protein-coding gene on chromosome 22 (27,748,277 to 27,801,756, reverse strand). Ensembl gene ENSG00000169184.
Subcellular location: Nucleus
Subcellular location (Human Protein Atlas): Nucleoplasm
Gene Ontology:
Molecular function: protein binding
Biological process: negative regulation of osteoblast proliferation; positive regulation of vitamin D receptor signaling pathway; regulation of cell cycle G1/S phase transition; regulation of DNA-templated transcription
Cellular component: nucleus
Genetic constraint (gnomAD): Loss-of-function variants: 19 observed, 57.85 expected, observed/expected ratio (o/e) 0.33, 90% interval 0.23 to 0.48. The synonymous counts are far from expectation, so gnomAD's model fits this gene poorly and the ratio says little. Missense variants: 1,841 observed, 1,597.4 expected, observed/expected ratio (o/e) 1.15, 90% interval 1.11 to 1.2. Synonymous variants: 928 observed, 736.7 expected, observed/expected ratio (o/e) 1.26, 90% interval 1.19 to 1.33.
Gene-disease validity (ClinGen):
ClinGen rates the evidence that MN1 causes each of these diseases.
CEBALID syndrome (autosomal dominant): Definitive.
Homologues: Orthologues: chimpanzee MN1 (99% identical), macaque MN1 (98% identical), dog MN1 (95% identical), guinea pig MN1 (93% identical), pig MN1 (90% identical), rat Mn1 (90% identical), mouse Mn1 (90% identical), tropical clawed frog mn1 (61% identical), zebrafish mn1b (52% identical), zebrafish mn1a (36% identical).
Diseases named in the same sentence as MN1 in open-access papers:
MN1 is named in the same sentence as 57 diseases in open-access papers, as found by Europe PMC text mining. Sharing a sentence is not in itself a finding about the gene and the disease. The quoted sentences say what the papers report.
astroblastoma (25 papers, 2018 to 2025). "Molecular genetic analysis of astroblastoma DNA or RNA using targeted next-generation sequencing reveals frequent MN1 mutations, often presenting as MN1-BEND2 fusion." (PMID 39963393, 2025). "Even so, more research is needed to establish distinct histopathological and molecular characteristics that can identify MN1-mutated astroblastomas from morphologically identical neuroepithelial tumors with similar genetic changes." (PMID 34638714, 2021). "This work contributes to the existing literature on astroblastomas associated with MN1 alterations." (PMID 39963393, 2025). "Therefore, WHO CNS5 has identified astroblastoma as “MN1-altered” to improve diagnostic clarity for this type." (PMID 34638714, 2021). "MN1-altered astroblastoma tumors have a miRNA expression signature that identifies a prognostic correlation, specific BPs, and molecular pathways in these tumors, revealing critical regulatory functions at multiple levels." (PMID 39857696, 2025). "In astroblastoma, the MN1 gene is usually rearranged in-frame with the BEND2 gene at chromosome Xp22.13, and less frequently with CXXC5." (PMID 39857696, 2025). "Recent studies have identified EWSR1-BEND2 fusion in astroblastoma, primarily located in the spinal cord or brain stem, categorized under MN1-altered astroblastoma methylation." (PMID 39963393, 2025). "The WHO CNS5 classification designates astroblastomas with MN1 alterations as a distinct molecular entity, yet further research is needed to differentiate them from other neuroepithelial tumors with overlapping genetic features." (PMID 40628732, 2025). "The MN1 gene, located on chromosome 22q, functions as a transcriptional coregulator and is frequently altered in astroblastomas, a rare glioma subtype predominantly affecting pediatric and young adult populations." (PMID 40628732, 2025). "Astroblastoma is a rare glial tumor characterized by structural rearrangements of the MN1 gene at chromosome 22q12.1." (PMID 39857696, 2025). "This case involves a 4-year-old girl diagnosed with astroblastoma harboring MN1 alteration, classified as a CNS WHO Grade 3 tumor." (PMID 40978059, 2025). "Here, we investigated microRNA expression, regulation, and biological processes correlated to target genes of deregulated miRNAs in MN1-altered astroblastoma." (PMID 39857696, 2025). "MN1-altered astroblastomas have limited outcome data, and specific clinical, histological, or molecular characteristics do not appear to be associated with outcomes." (PMID 38544524, 2024). "Some are already introduced in the WHO CNS5 such as MN1 oncogenic fusions defining Astroblastoma MN1-altered." (PMID 39409964, 2024). "More than 60% of MN1 fusion-positive CNS tumors show astroblastoma morphology characterized by astroblastic perivascular pseudorosettes but astroblastomas, such MN1-altered astroblastomas, remain a rare, heterogenous and poorly characterized tumor group." (PMID 39409964, 2024). "For example, astroblastomas-MN1 altered, molecular subtypes of ependymoma and medulloblastoma subgroups require this advanced testing." (PMID 38427131, 2024). "EWSR1::BEND2 fusions are recurrent in a specific subtype of astroblastoma that is closely related to ‘astroblastoma, MN1-altered′, an entity that harbors MN1 GF with BEND2 as the typical partner, but they are slightly different in their methylation profile." (PMID 38339014, 2024). "In the fifth CNS WHO classification, MN1 is part of the diagnosis of a “circumscribed astrocytoma”, Astroblastoma MN1-altered, characterized by fusions of MN1 with BEND2 or CXXC5 genes." (PMID 39409964, 2024). "Astroblastoma are molecularly characterized by the rearrangements of the MN1 gene at chromosome band 22q12.1 and gene fusion involving MN1." (PMID 36831464, 2023).
astroblastoma (continued). "This was exemplified in our patient with an MN1 fusion-positive astroblastoma (P2058), where global methylation profiling was uninformative, and targeted MN1 testing would have missed the second gene fusion detected, EWSR1-PATZ1." (PMID 35449451, 2022). "This latter group was specifically associated with gene fusions involving MN1 (22q12.3), usually with BEND2 (Xp22.13), but also the alternative partner CXXC5 (5q31.2), and contained 16/23 cases diagnosed as astroblastoma by the originating centres." (PMID 29348602, 2018). "The diagnoses included 3 pilocytic astrocytomas, 1 diffuse low-grade glioma, MAPK pathway-altered, 1 polymorphous low-grade neuroepithelial tumor of the young, 1 astroblastoma, MN1-altered, 1 desmoplastic infantile astrocytoma, and 1 diffuse leptomeningeal glioneuronal tumor." (PMID 40980447, 2025). "Our findings suggested that the involved pathways could be associated with clinical and pathological characteristics of MN1-altered astroblastomas." (PMID 39857696, 2025). "Since similar histological features may be present in other tumors with different molecular alterations and prognosis, the detection of MN1 rearrangement represents a fundamental molecular approach for the diagnosis of astroblastoma." (PMID 39857696, 2025). "We presented a case of high-grade pediatric MN1-altered, BRCA2-mutated astroblastoma managed with maximal safe resection, adjuvant proton beam therapy including craniospinal irradiation, chemotherapy, and subsequent salvage Gamma Knife radiosurgery for residual disease." (PMID 40978059, 2025). "Astroblastoma, MN1-altered, is a rare circumscribed glial tumor harboring MN1 alterations." (PMID 38544524, 2024). "Moreover, in astroblastoma or neuroepithelial tumors, patients with MN1 rearrangement were reported to have longer survival and better prognosis." (PMID 35677036, 2022). "Alterations in MN1 frequently occur in astroblastoma, a type of gliomas." (PMID 34638714, 2021). "By using DNA methylation profiling, a subset of CNS high-grade tumors with astroblastoma-like morphology characterized by the meningioma 1 gene (MN1) rearrangements, has been identified; they were termed “CNS high-grade neuroepithelial tumors with MN1 alteration” (CNS-HGNET-MN1)." (PMID 31114608, 2019). "MN1 rearrangements could be confirmed in four of these cases, and neuropathological re‐evaluation of these cases showed features of astroblastoma (according to the WHO classification)." (PMID 30325077, 2019). "Notably, the 2021 WHO classification of central nervous system tumors has integrated molecular diagnostics, recognizing “astroblastoma, MN1-altered” as a distinct entity within the category of circumscribed astrocytic gliomas, characterized by the presence of meningioma 1 (MN1) gene alterations." (PMID 40978059, 2025). "We conducted a retrospective study of histology and immunohistochemistry, focusing on MN1 fusion-positive astroblastoma (MN1-BEND2 fusion), EWSR1 fusion-positive astroblastoma (EWSR1-BEND2 fusion), and other subtypes." (PMID 39963393, 2025). "This translocation is typical of astroblastomas; cases of MN1::BEND2 (also typical of astroblastomas) and MN1::TAF3 fusions have begun to be described in soft tissue sarcomas." (PMID 40141463, 2025). "In decreasing order of frequency, EWSR1, MN1, and MAMLD1 are the reported fusion partners of BEND2 in astroblastoma-like gliomas." (PMID 36690805, 2023). "In the present case, the diagnoses of ependymoma and MN1‐altered astroblastoma were excluded because of the lack of perivascular pseudorosettes and ZFTA, YAP1, and MN1 fusions." (PMID 39492623, 2025). "Another tumor (patient #30) initially diagnosed as grade 2 astroblastoma was reclassified as LGG in the absence of MN1 alteration." (PMID 38440233, 2024). "Another tumor initially diagnosed as grade 2 astroblastoma grade 2 was reclassified as low-grade-glioma in the absence of MN1 alteration." (PMID 38440233, 2024).
astroblastoma (continued). "Consequently, much like in astroblastomas, the EWSR1::BEND2 and MN1::BEND2 fusions may define a distinct subgroup of mesenchymal tumors." (PMID 38339014, 2024). "Chromothripsis may also be responsible for generating chromosome 22q fusions in rare supratentorial astroblastoma-like tumors lacking MN1 alterations and chromosome 11q13.1 gene fusions in ZFTA-RELA harboring supratentorial ependymomas." (PMID 36604386, 2023).
leukemia (19 papers, 2009 to 2025). A malignant (clonal) hematologic disorder, involving hematopoietic stem cells and characterized by the presence of primitive or atypical myeloid or lymphoid cells in the bone marrow and the blood. "We previously found that loss of Kmt2a led to downregulation of the aberrant “MN1-driven leukemic program”, suggesting that the aberrant expression of Hoxa9 and Meis1 in MN1-driven leukemia remained under the control of its physiologic regulator, Kmt2a." (PMID 33542482, 2021). "In this study, we sought to identify and characterise additional genes underlying leukemias derived from overexpression of the potent oncogene MN1." (PMID 28960191, 2017). "Eight genes (BAALC, CD14, CD34, CD74, DNTT, HLA-DRA, IRF8, and MN1) were all associated with “leukemia” (P = 1.15 × 10−4), “acute myeloid leukemia” (P = 9.37 × 10−3), and “proliferation of myeloid cells” (P = 0.044)." (PMID 26517675, 2015). "MN1-TEL is considered the prototype of leukemia-associated fusions to which TEL contributes its DBD." (PMID 23049943, 2012). "The leukemia-associated fusion protein MN1-TEL combines the transcription-activating domains of MN1 with the DNA-binding domain of the transcriptional repressor TEL." (PMID 23049943, 2012). "Furthermore, GSEA revealed that a set of genes that we had previously found to be downregulated upon loss of Kmt2a in MN1-driven leukemia was enriched in Men1−/− versus Men1wt MN1-driven AML cells." (PMID 33542482, 2021). "Forced expression of MN1 in murine bone marrow causes the development of an aggressive leukemia." (PMID 33542482, 2021). "Forced expression of MN1-TEL in mice causes leukemias and lymphoid tumors." (PMID 23049943, 2012). "When overexpressed in murine hematopoietic progenitors, MN1 causes an aggressive AML characterized by an aberrant myeloid precursor-like gene expression program that shares features of KMT2A-rearranged (KMT2A-r) leukemia, including high levels of Hoxa and Meis1 gene expression." (PMID 33542482, 2021). "MN1 proto-oncogene, transcriptional regulator (MN1) is a transcriptional coregulator that has rearrangements in meningioma and leukemia." (PMID 35169893, 2022). "We previously established that aberrant gene expression in MN1-driven leukemia was under the control of wild type Kmt2a." (PMID 33542482, 2021). "Collectively, these results nominate Menin inhibition as a promising therapeutic strategy in MN1-driven leukemia." (PMID 33542482, 2021). "Pharmacologic inhibition of the KMT2A–Menin interaction decreased colony-forming activity, induced differentiation programs in MN1-driven murine leukemia and decreased leukemic burden in a human AML xenograft carrying an MN1-ETV6 translocation." (PMID 33542482, 2021). "MN1-driven leukemia is characterized by a CMP-like gene expression program that includes high expression of Hoxa9 and Meis1, known target genes of Kmt2a-fusion proteins but also of wild type Kmt2a." (PMID 33542482, 2021). "We previously found that deletion of Kmt2a in MN1-driven leukemia led to a downregulation of the MN1-driven leukemic program." (PMID 33542482, 2021). "Menin was found to be essential for transformation and maintenance of KMT2A-rearranged leukemias and our previous findings suggest that endogenous Kmt2a is required for MN1-driven leukemia." (PMID 33542482, 2021). "A similar gene expression requirement exists in human CD34 + cord blood cells, where MN1 alone is insufficient to induce leukemia but needs cooperation with high HOX cluster gene expression mediated for example by the NUP98-HOXD13 fusion." (PMID 33542482, 2021). "In secondary recipients, the decrease in LIC resulted in an almost complete exhaustion of Men1−/− MN1-driven leukemia cells in vivo." (PMID 33542482, 2021). "MN1 is also a potent and sufficient oncogene in murine leukemia models, strongly dependent on the MEIS1/AbdB-like HOX protein complex to transform common myeloid progenitors, block myeloid differentiation, and promote leukemic stem cell self-renewal." (PMID 28960191, 2017).
leukemia (continued). "Using gene expression profiling of these subsets combined with previously published comparisons of full-length MN1 and mutants with varying leukemogenic activity, we identified candidate genes critical to leukemia." (PMID 28960191, 2017). "Knockout studies of Mn1 revealed that the leukemia phenotype of the gene is only a by-product of a particular fusion with another gene, while the core function of Mn1 lies in regulating the development of membranous bones of the cranial skeleton." (PMID 26523602, 2015). "The ability of MN1 to induce rapid onset leukemia on its own highlights its central regulatory role in hematopoietic transformation." (PMID 25401736, 2014). "This deleted region partially overlaps with our MN1Δ5-7 mutant, supporting the idea that the MN1 C-terminus promotes a myeloid-skew to MN1 leukemia." (PMID 25401736, 2014). "Despite the established role of MN1 overexpression in leukemia, little is known about the protein itself." (PMID 25401736, 2014). "Here, we systematically localise known properties of MN1 leukemia using both in vitro and extensive in vivo studies to specific physical regions of wildtype MN1 through a detailed structure-function analysis of MN1." (PMID 25401736, 2014). "To delineate the sequences within MN1 necessary for MN1-induced leukemia, we tested the transforming capacity of in-frame deletion mutants, using retroviral transduction of mouse bone marrow." (PMID 23626719, 2013). "MN1 and NF2 have previously been implicated in the development of leukemia and solid tumors, and ZNRF3 and KREMEN1 are inhibitors of the Wnt/beta-catenin signaling pathway." (PMID 24236197, 2013). "Indeed, pharmacologic inhibition of the Menin/Kmt2a interaction decreased colony formation and leukemia burden in models of murine and human MN1-driven AML in vivo and in vitro, respectively." (PMID 33542482, 2021). "In addition, genes bound by the histone methyltransferase DOT1L and downregulated upon Menin inhibition in KMT2A-MLLT3 leukemia were found to be enriched in Men1−/− versus Men1wt MN1-driven AML." (PMID 33542482, 2021). "However, we identified Meis2 as critical to MN1-induced leukemia, with essential roles in proliferation, self-renewal, impairment of differentiation and disease progression in vitro and in vivo." (PMID 28960191, 2017). "Conversely, the N-terminal sequence up to amino acid 317 (MN1Δ3-7) was sufficient to induce strong myeloproliferation with high WBC counts and large spleen with full myeloid differentiation potential, demonstrating that the MN1 N-terminus is driving proliferation in MN1 leukemia." (PMID 25401736, 2014). "We dissected the functional aspects of different protein regions of the MN1 oncogene and their effect on the leukemic phenotype, building on the ability of MN1 to induce leukemia without accompanying mutations." (PMID 25401736, 2014). "Future studies that will identify the proteins interacting with MN1, the domains within MN1 required for their interaction, and validation of the role of these potential players in MN1-induced leukemia will further increase our understanding of the precise role of MN1 overexpression in AML." (PMID 23626719, 2013). "FLT3 and c-Kit signaling direct MN1-expressing cells toward the myeloid lineage, so disruption of these signals may prevent leukemia." (PMID 24367366, 2013). "Therefore, understanding whether the SET domain plays a role in MN1-driven leukemia could have future therapeutic implications." (PMID 33542482, 2021). "Therefore, we next investigated whether the Kmt2a N-terminal interaction partner Menin was required in MN1-driven leukemia." (PMID 33542482, 2021).
leukemia (continued). "This was accomplished by comparing the transcriptome of highly purified common myeloid progenitors (CMP) overexpressing MN1 or a MN1 deletion mutant, which induced myeloproliferation and prevented myeloid differentiation invitro, but did not cause leukemia in mice." (PMID 23626719, 2013). "Furthermore, Men1−/− MN1-driven AML cells failed to propagate leukemia in most recipients (13/15), with a failure to rearrange both alleles in one of the animals." (PMID 33542482, 2021). "Thus, the SET domain of Kmt2a (and therefore the corresponding histone methyltransferase activity) is not required for the establishment of MN1-driven leukemia in vitro or in vivo." (PMID 33542482, 2021). "Despite its increased self-renewal and myeloproliferative activity in vitro, mice receiving transplants of Δ12–228-expressing bone marrow (transduction rate of the transplanted cells were similar to that of full length MN1) did not develop leukemia in two independent experiments." (PMID 23626719, 2013). "The exact mechanism is still unknown and there are some putative mechanisms for this phenomenon involving in overexpression of MN1, mutations of RARa as noted in HL-60 cells, selection of non-APL leukemia clones and increased expression of proteins involved in ATRA's metabolism." (PMID 19435509, 2009).